H2BW1 (H2B.W histone 1)
Description:
Atypical histone H2B that can form nucleosomes structurally and dynamically indistinguishable from those containing conventional H2B. Nucleosomes wrap and compact DNA into chromatin, limiting DNA accessibility to the cellular machineries which require DNA as a template. Histones thereby play a central role in transcription regulation, DNA repair, DNA replication and chromosomal stability. DNA accessibility is regulated via a complex set of post-translational modifications of histones, also called histone code, and nucleosome remodeling. However, unlike conventional H2B, does not recruit chromosome condensation factors and does not participate in the assembly of mitotic chromosomes. May be important for telomere function and play a role in spermatogenesis.
Synonyms: H2BFWT; TH2B-175
Tractability: No criterion of Open Targets' tractability assessment is met for any kind of drug.
Gene: Protein-coding gene on chromosome X (104,011,147 to 104,013,708, reverse strand). Ensembl gene ENSG00000123569.
Subcellular location: Nucleus membrane; Chromosome; Chromosome, telomere
Gene Ontology:
Molecular function: protein binding; structural constituent of chromatin; DNA binding; protein heterodimerization activity
Biological process: mitotic chromosome condensation; chromatin organization
Cellular component: chromosome; chromosome, telomeric region; nuclear membrane; nucleosome; nucleus
Homologues: Orthologues: chimpanzee H2BW4 (97% identical), macaque H2BW1C (90% identical), macaque H2BW1 (86% identical), mouse H2bw2 (39% identical). Paralogues in human: H2BW2 (72% identical), H2BC11 (39% identical), H2BC12 (39% identical), H2BC12L (39% identical), H2BC15 (39% identical), H2BC26 (39% identical), H2BC3 (39% identical), H2BC10 (38% identical), H2BC17 (38% identical), H2BC18 (38% identical), H2BC21 (38% identical), H2BC4 (38% identical), and 9 more.